TNF (tumor necrosis factor)
Diseases named in the same sentence as TNF in open-access papers (continued):
Sharing a sentence is not in itself a finding about the gene and the disease.
acne (continued). "TNF-α, IL-6 and IL-1β are inflammatory molecules involved in both acute and chronic inflammatory acne." (PMID 36145700, 2022). "Proinflammatory cytokines such as IL-1β, IL-6, IL-8, and TNF-α are responsible for the follicular keratinization and inflammation of acne." (PMID 35947554, 2022). "Typical cytokines from neutrophils, macrophages, and epithelial cells, such as TNF-α and IL-1β, are elevated in acne lesions." (PMID 35740016, 2022). "Pro-inflammatory cytokines, such as IFN-γ, TNF-α, IL-6, and IL-8, are already known to be upregulated in acne lesions." (PMID 35328573, 2022). "The inflammatory response to the recognition of P. acnes in TLR2 contributes to the inflammatory nature of acne by inducing monocytes to secrete pro-inflammatory cytokines including TNF-α, IL-1, and IL-8." (PMID 35269651, 2022). "In acne inflammation pathogenesis, C. acnes plays an important trigger role through IL-6 and IL-8 secretion by follicular keratinocytes and IL-1β, TNF-α, IL-8 and IL-12 by monocytes." (PMID 36145700, 2022). "A cytokine mRNA analysis revealed that facial acne lesions had evidence of significantly greater levels of tumor necrosis factor-α (TNF- α) and interleukins." (PMID 34207527, 2021). "The results indicate that TAN has therapeutic efficacy for acne, as supported by the results of the histological analyses and biochemical index assays for interleukin (IL)-8, IL-6, IL-β and tumor necrosis factor alpha." (PMID 34177586, 2021). "Nitrate oxide can be an alternative treatment for acne in humans by reducing IL-1β, IL-8, TNF-α, and IL-6 induced by monocytes and IL-8 and IL-6 induced by keratinocytes via innate immunity." (PMID 32765835, 2020). "Immunological studies of acne have generated innovative immunity induction therapies such as antibodies to TNF-α and various cytokines." (PMID 32765835, 2020). "The most refractory complication of acne is scar formation, which involves the production of pro-inflammatory cytokines such as IL-1α, IL-1β, IL-6, TNF-α, and TGF-β54." (PMID 32765835, 2020). "Compared to normal skin, the expression of TNF in acne lesions is increased; TNF also induces the formation of lipid droplets in sebocytes." (PMID 32685503, 2020). "The overexpression of CCL2 originated from activated TNF signaling pathway and S100A7 with chemotactic activity probably associates with some patients' side effects of “acne-flare” in early stage of isotretinoin treatment." (PMID 32685503, 2020). "The present study is the first to evaluate the serum levels of IL-1α, IL-1β, IL-6, IL-8, IL-12β, IL-15, TNF-α, and granulocyte-macrophage colony-stimulating factor in acne subjects compared with the levels in healthy controls." (PMID 31951642, 2020). "We believe that treating lesions with RF or IPL can reduce TNF-α, and will contribute to mitigating the progression of acne lesions." (PMID 30911021, 2019). "Further studies are needed to explore the correlation between MMP-2 activity and expression of IL-1a and β, TNF-α, and triglycerides in acne." (PMID 31032338, 2019). "MMP-2 is now recognized to cleave a large number of non-matrix substrates, including IGFBPs, IL-1β, pro-IL-1β, latent TGF-β, and latent TNF-α, which are the main factors in acne inflammation." (PMID 31032338, 2019). "It contributes to the inflammatory response of acne by stimulating the production of inflammatory cytokines like IL-8, IL-1β and TNF-α from keratinocytes, sebocytes, and inflammatory cells." (PMID 31252651, 2019). "P. acnes contributes to the inflammatory nature of acne by inducing monocytes to produce proinflammatory cytokines, such as tumor necrosis factor (TNF)-α, interleukin (IL)-1β, and IL-8." (PMID 30987239, 2019). "Sand and Thomsen reported benefit from TNF-α inhibitors in 64% (7/11) of patients with severe refractory acne conglobata." (PMID 31440261, 2019).
acne (continued). "During acne inflammatory reaction, P. acnes induces the production of pro-inflammatory cytokines such as interleukin (IL)-1β, IL-6, IL-8, and tumor necrosis factor (TNF)-α in monocytes and keratinocytes." (PMID 30261862, 2018). "A research in vivo reported that a marked increase for tumor necrosis factor (TNF) gene transcripts was observed in acne lesions." (PMID 24498378, 2014). "The proinflammatory cytokines IL-1β, IL-6, TNF-α and the chemokine IL-8 were all expressed at a higher level in acne lesions in the Finnish cohort." (PMID 25153527, 2014). "Our results are in line with the prior observations concerning up-regulated TNF-α and IL-1β in acne lesions examined by RT-PCR." (PMID 25153527, 2014). "A number of proinflammatory cytokines, including interleukin-6 (IL-6), tumor necrosis factor-α (TNF-α), and interleukin-1β (IL-1β), have been implicated in the inflammatory process of acne." (PMID 24078775, 2013). "These two cytokines (TNF-α and IL-1β) propagate the acne inflammatory response by acting on endothelial cells to elaborate adhesion molecules to facilitate recruitment of inflammatory cells into the skin." (PMID 24078775, 2013). "Inflammatory acne was regulated by inflammatory factors including TNF-α and IL-1β, which are secreted by monocytes." (PMID 24013774, 2013). "Enhanced androgen, TNF-α and IGF-1 signalling due to genetic polymorphisms promoting the risk of acne all converge in mTORC1 activation, which is further enhanced by nutrient signalling of WD." (PMID 23614736, 2013). "In view of the inhibition of the signaling pathway, side effects have emerged, such as herpes zoster infection, cytopenias, or even cancers in comparison with anti-tumor necrosis factor (anti-TNF) in inflammatory diseases, and more recently acne, whatever the active disease, including AD." (PMID 39980606, 2025). "The elevated levels of Hs-CRP observed in severe-grade acne in our study may be attributed to the increased number of inflammatory lesions and the concurrent elevation of cytokines such as IL-6 and TNF-α, which stimulate the hepatic production of CRP." (PMID 40851686, 2025). "Myeloid cells play important roles in acne development by responding to Propionibacterium acnes (P. acnes) and producing proinflammatory factors such as interleukin (IL)−1β, IL-6, IL-8, and tumor necrosis factor α (TNFα), which contribute significantly to acne inflammation." (PMID 41307843, 2025). "In acne-induced PS formation, the expression of anti-inflammatory cytokines such as IL-10 decreases and the expression of proinflammatory cytokines such as TNF-α increases; these factors have been shown to play crucial roles in the development of acne-induced PSs." (PMID 38585341, 2024). "The results of enrichment analysis showed that the treatment of acne with PAD may be related to TNF signaling pathway and AGE-RAGE signaling pathway." (PMID 39029003, 2024). "The core targets of the treatment of acne were TNF, GADPH, IL-6 and so on." (PMID 39029003, 2024). "The inflammatory factors IL-1β and TNF-α have a close relationship with the pathogenesis of acne." (PMID 37894244, 2023). "Apparently, IL-8 and TNF-α play an essential role in the pathophysiology of acne." (PMID 35211023, 2022). "HVE (5–250 μg/mL) also demonstrated inhibitory activity against the NF-κB-driven transcription and the correlated IL-6 and IL-8 release in keratinocytes challenged with C. acnes infection or TNF-α, suggesting a possible role against the topical inflammation occurring in acne." (PMID 35740016, 2022). "TNFα is an important pathophysiologic factor involved in the development of acne." (PMID 36439142, 2022). "TNF-α and IL-8 are important cytokines in the inflammatory response of acne." (PMID 35211023, 2022). "Cytokines like TNF-α and IL-8 have an important role in the development of inflammation of acne." (PMID 35211023, 2022).
acne (continued). "Thus, cytokines orchestrating the immune response in acne includes Interleukin 1β (IL-1β), Interleukin 6 (IL-6), Interleukin 8 (IL-8), and Tumor Necrosis Factor alpha (TNFα) involved in the inflammatory pathogenesis." (PMID 35910763, 2022). "In addition, the Western blot test showed that LCF significantly inhibited the upregulation of IL-8 and TNF -α levels in the skin of acne rats, thereby inhibiting inflammation." (PMID 35211023, 2022). "This systematic review and meta-analysis suggest that genes influencing inflammatory responses, specifically TNF, and genes influencing the function and activity of sebaceous glands, specifically CYP17A1 and FST, have potential risk variants for acne presentation and severity across populations." (PMID 33849530, 2021). "The results are comparable to previous findings that RF irradiation reduced TNF-α expression in an acne-induced rabbit ear model, but there are few studies showing that RF modulates the expression of HMGB1 and TLRs, which are key molecules in skin inflammation." (PMID 33670841, 2021). "Begg’s funnel plot and Egger’s test showed that there was statistically significant publication bias for the meta-analysis of TNF rs1800629 acne presentation, mild acne and severe acne; SELL rs7531806; PPARG rs1801282; and CYP17A1 rs743572 acne presentation, moderate acne and severe acne." (PMID 33849530, 2021). "From these immunological aspects in acne, Th1, Th17, and TNF-α are upregulated in acne." (PMID 32765835, 2020). "Th1 and Th17 shift inhibitors and antibodies against IL-17 and TNF-α might offer alternative approaches to treating acne." (PMID 32765835, 2020). "IL-17 is reduced by vitamins A and D. IL-1β and TNF-α are involved in acne inflammation." (PMID 32765835, 2020). "Use of the RF on acne also resulted in attenuated TNF-α release in an acne model." (PMID 30911021, 2019). "Additionally, peripheral blood mononuclear cells (PBMCs) of acne patients stimulated with P. acnes produce increased amounts of TNF-α and IL-8 pointing to the central role of TNF-α in this condition." (PMID 31440261, 2019). "TNF-α is a multifunctional cytokine related to the regulation of acne inflammation." (PMID 30120655, 2019). "Our study suggests that MMP-2 CT/TIMP-2 GG genotype may correspond to decreased activity of MMP-2, which may lead to the high expression of IL-1a and β, TNF-α, and triglycerides observed in acne patients." (PMID 31032338, 2019). "Decreased MMP-2 activity may lead to the production of cytokines such as IL-1β, Pro-IL-1β, TGF-β, latent TNF-α, and elevated triglycerides, which are the key modulators in acne." (PMID 31032338, 2019). "On the other hand, tumor necrosis factor-α (TNF-α) seems to play a minor role in acne inflammation." (PMID 25894228, 2015). "Similarly, TLR2 and TLR4 as well as IL-8, IL-6, and TNF-α, were induced in acne lesions in the German group." (PMID 25153527, 2014). "Besides IL-6, we also found that TNF-α and IL-1β were increased following PA treatment, which are also critically important in acne inflammation." (PMID 24078775, 2013). "The Zn-de-Model group exhibited higher levels of these cytokines than the Model group, with increases of 51.74% for TNF-α, 11.91% for IL-1β, 118.06% for IL-17A, 19.64% for MMP9, and 17.05% for CXCL1/KC, indicating that Zn deficiency leads to more severe skin inflammation in acne-like mice." (PMID 40507073, 2025). "Although the pathogenesis of SAPHO syndrome is unclear, studies suggest that proinflammatory cytokines such as IL-8 and TNF-α may be triggered by Cutibacterium acnes infection and lead to skin lesions such as acne conglobata and a systemic inflammatory response." (PMID 39808231, 2025). "Indeed, in human keratinocytes, its expression is stimulated by cytokines typical for the acne inflammatory milieu, such as TNF-α, IFN-γ, and IL-1β, indicating that inflamed skin may trigger its production in the epidermis." (PMID 39744637, 2024).
acne (continued). "In particular, the studies investigated variations at positions − 238, − 308, − 857, − 863 and − 1031 localized in the promoter region of TNF, meaning that they may affect the gene expression positively or negatively, conferring a protective or detrimental effect on acne." (PMID 33849530, 2021). "Nevertheless, we found that TNF rs1800629 A allele carriers and CYP17A1 rs743572 T allele carriers had significantly reduced mild acne risk [pOR: 0.60; 95% Confidence Interval (CI): 0.33–0.86] and severe acne risk (pOR: 0.59; 95% CI: 0.40–0.79), respectively, across populations." (PMID 33849530, 2021). "Moreover, they suggested that anti-TNF-a agents is supposed to become potential therapeutic strategies to control seborrhea, which is also a common skin inflammatory disease, characterized by excessive secretion of sebum by sebocytes, similar to acne." (PMID 34067630, 2021). "Because TNF-α is known to have an important role in oxidative stress, and in the initiation of inflammatory and immunological processes which are also involved in acne pathophysiology, G. amansii represents an opportunity to address multi targets of AV disease." (PMID 34834345, 2021). "It downregulates TNF-α, IL-6, PGE2, and COX-2 and is widely incorporated into anti-acne and soothing skin-care formulations." (PMID 41007180, 2025). "It acts against the main factors contributing to the pathogenesis of acne by inhibiting pro-inflammatory mediators (e.g., COX-2, PGE2, IL-1β and TNF-α)." (PMID 39596008, 2024). "Existing studies have shown that intervention treatment with IAA significantly reduces the expression level of TNF-α in NAFLD, dental pulp stem cells, and rat model of acne vulgaris, thereby attenuating the inflammatory response and oxidative stress levels." (PMID 39568012, 2024). "TNF-α, an important modulator of MMP activity in the dermis, was found to have a five-fold increase in acne lesions compared to healthy skin." (PMID 39519131, 2024). "PPAR-γ, TNF, IL-1β, IL-6, TLR and NFκB1 were identified as potential core targets of GA in the regulation of acne vulgaris." (PMID 38792208, 2024). "Based on the PPI network analysis and topology algorithm in Cytoscape software, TNF, GAPDH, IL6, Albumin (ALB), and protein kinase 1 (AKT1) are considered to be the core target proteins for the treatment of acne." (PMID 39029003, 2024). "It was found that baicalin significantly decreased the expression of M1 macrophage-related cytokines such as IL-1β, IL-6, TNF-α and NLRP3 in acne models, and inhibited the M1 polarization of macrophages by inhibiting the nuclear translocation of NF-κB p65." (PMID 38736879, 2024). "The combination of TNF inhibitors and ALA-PDT or adalimumab has shown promising results in treating inflammatory skin conditions, including severe and refractory acne vulgaris, as per recent studies." (PMID 37250640, 2023). "In the interaction between TLR2 and P. acnes, NF-κB acts as an essential TLR2 downstream signal that has a major impact on inflammatory responses in acne by releasing various pro-inflammatory cytokines such as COX-2, iNOS, IL-1β, and TNF-α." (PMID 35269651, 2022). "Several inflammatory cytokines such as TNF-α, IL-1β, COX-2 are known to be responsible for follicular hyper-keratinization and are involved in the process of changing these acne lesions." (PMID 35269651, 2022). "Previous studies showed that important inflammatory molecules, such as IL6, IL8, TNFα, 5-lipoxygenase (5LOX) or cyclooxygenase 2 [COX2; a.k.a. prostaglandin-endoperoxide synthase (PTGS2)] are increased in lesional sebocytes of acne patients." (PMID 36439142, 2022). "This patient presented at adolescent age with severe acne and pustulosis which improved with oral corticosteroid, MTX and TNF-α blockade." (PMID 35698069, 2022). "Tumor necrosis factor inhibitors are usually used as a second-line therapy for refractory SAPHO syndrome and has been reported to treat acne conglobata successfully." (PMID 36224598, 2022).
acne (continued). "It is known that tumor necrosis factor-alpha (TNF-a) is involved in the formation of acne and increasing cases has reported the efficacy of anti-TNF-a agents in the management of moderate to severe acne." (PMID 34067630, 2021). "A previous study showed that the aryl hydrocarbon receptor promotes secretion of inflammatory factors TNF-α and IL-8 in human SZ95 sebocytes, which indicates a possible mechanism in TLR2-mediated acne." (PMID 32685503, 2020). "In clinical acne samples, P. acnes triggers activation of TLR-2 which modulates production of inflammatory cytokines, including TNF-α, IL-1β, IL-6, and IL-87,30." (PMID 29507345, 2018). "A total of 37 potential targets were predicted by network pharmacology, among which TNF, IL-1B, IL-6, ESR1, PPARG, NFκB1, STAT3, and TLR4 may be the key targets of GA in the treatment of acne." (PMID 38792208, 2024). "Besides, isoglycyrrhizin inhibits inflammatory cytokines like IL-6, IL-8, TNF-α and IL-1β in NF-κB, p38 and ERK pathways in multi cells, all of which have been reported to be closely related to acne." (PMID 35211023, 2022). "In the comparison MDL group, the expression levels of TNF-α and IL-8 in both skin and serum were significantly decreased (p < .05) after treatment with LCF, indicating that LCF can inhibit the inflammatory response in acne." (PMID 35211023, 2022). "Studies have shown that TNF-α and IL-8 levels in patients with acne are significantly higher than in people without acne." (PMID 35211023, 2022). "As shown in the cytokine levels in serum of IL-6, IL-8, TNF-α and IL-1β, the CPT could inhibit the release of these cytokines, thus improving inflammation in acne rats." (PMID 34539397, 2021). "Suppression of the TNF signaling pathway and S100A7 might be an alternative option for inhibiting “acne-flare” of acne patients while using isotretinoin." (PMID 32685503, 2020). "Using isotretinoin for 1 week, LCN2, PTGES, and GDF15 were upregulated and might mediate sebocytes apoptosis and thus decreased sebum production; CCL2 originated from activated TNF signaling pathway and S100A7 could be related with “acne-flare”." (PMID 32685503, 2020). "In comparisons of lesional skin of individuals with classic ulcerative PG and PG, acne, and suppurative hidradenitis (PASH) syndrome, both showed overexpression of IL-1β, tumor necrosis factor alpha (TNFα), IL-17, endothelial- and leukocyte-selectin, and chemokines IL-8, CXCL16, and RANTES17,18." (PMID 31885859, 2019). "In addition, although IPL treatment is less destructive of the sebaceous gland than RF, it is believed to aid the treatment of acne through increasing TGF-β, decreasing TNF-α, and increasing PPAR-γ." (PMID 30911021, 2019). "Moreover, nuclear factor (NF)-κB, activator protein (AP)-1, pro-inflammatory cytokines (TNF-α, IL-1β, IL-6, and IL-8), and metalloproteinases (MMP) are activated via upregulation of TLR-2 in facial acne lesions of patients." (PMID 29507345, 2018). "Moreover, the increased expression of cytokines and other inflammatory markers such as IL-1α, beta-defensins 1 and 2, TNF-α, IL-1β, IL-8, IL-10, matrix metalloproteinases MMP-1, MMP-3, MMP-9, CXCL-2 was found in acne lesions in vivo." (PMID 25153527, 2014). "Furthermore, Th17 cell products IL-17A, IL-22, IL-26, TNF and IL-17 induced chemokines CSF2 and CCL20 were also expressed at higher levels in acne lesions." (PMID 25153527, 2014). "In conclusion, this study exhibits that the upregulated expression of LCN2, PTGES, and GDF15 might mediate sebocytes apoptosis and thus decreased sebum production; while CCL2 originated from activated TNF signaling pathway and S100A7 could be related with “acne-flare” using isotretinoin for 1 week." (PMID 32685503, 2020). "When the data were evaluated for shifts from probiotic exposure in those with acne, there were no significant shifts in FABP-2, TNF-alpha, or LPS, but there was a trend toward an increase in zonulin (p = 0.052)." (PMID 36769543, 2023).